TDP1 (tyrosyl-DNA phosphodiesterase 1)
Diseases named in the same sentence as TDP1 in open-access papers (continued):
Sharing a sentence is not in itself a finding about the gene and the disease.
cancer (continued). "Human cancer cells use both proteasome‐dependent and proteasome‐independent endonucleolytic pathways (TDP1, PARP1, XPF‐ERCC1, MRE11, CTIP, and MUS81‐EM1) to remove TOP1cc." (PMID 35582959, 2022). "Tyrosyl-DNA phosphodiesterase 1 (TDP1) is believed to be responsible for making cancer cells resistant since this enzyme cleaves the TOP1–DNA covalent complex, thereby repairing DNA damage mediated by TOP1 poisons." (PMID 35684313, 2022). "TDP1 inhibitors can potentiate the combined anticancer activities of Top1-target anticancer drugs and overcome cancer cell resistance to therapeutic drugs in some cancers." (PMID 35323510, 2022). "In the present work, we have shown for the first time that a derivative of a nucleoside inhibiting Tdp1 sensitizes mice Krebs-2 ascitic carcinoma cells to the action of the Top1 inhibitor Tpc used in the clinic." (PMID 36615517, 2022). "On the one hand, Tdp1 is overexpressed in some types of cancer, such as non-small lung cancer and glioblastoma." (PMID 34073771, 2021). "Together with topoisomerase inhibitors, NSC120686 has been used as a pharmacophoric model to suppress the TDP1 activity as part of a synergistic treatment for cancer therapies whereas, in plants, dose-dependent genotoxicity was evidenced." (PMID 33767724, 2021). "An interesting target for cancer treatment is TDP1, which plays a key role in the removal of DNA damage produced by TOP1 inhibition by clinically important anticancer drugs (irinotecan, Tpc) as well as removal of DNA damage caused by other anticancer drugs." (PMID 34356597, 2021). "The review of Brettrager and van Waardenburg in this issue focuses on Tdp1 and its potential as an anti-cancer target." (PMID 34532656, 2021). "The effect of the Tdp1 inhibitors at 5 μM on the 50% cytotoxic concentration (CC50) value of topotecan for HeLa cancer cells." (PMID 34073771, 2021). "Due to its repair action mechanism, TDP-1 is related to resistance to TOP I inhibitors during cancer treatments." (PMID 33536086, 2021). "This indicates that low doses of all three TDP1 inhibitors can kill cancer cells when combined with a low dose of TOP1 poison." (PMID 34300575, 2021). "UCHL3 enhanced the DNA damage repair mediated by radiotherapy and chemotherapy in cancer cells via binding to tyrosyl DNA phosphodiesterase 1 (TDP1), a chromosome breakage repair related enzyme, and mediating TDP1 deubiquitination." (PMID 32351584, 2020). "Tyrosyl-DNA phosphodiesterase 1 is regarded now as the highly potential target for inhibition in cancer cells." (PMID 33505969, 2020). "Tyrosyl-DNA-phosphodiesterase 1 (TDP1) is a DNA repair enzyme and a promising therapeutic target to enhance established cancer treatment." (PMID 32751997, 2020). "They concluded that UCHL3 regulates physiological Tdp1 enzyme levels, with low UCHL3/Tdp1 levels to be associated with neurodegeneration and elevated levels of UCHL3/Tdp1 to be associated with cancer." (PMID 31698852, 2019). "Intriguingly, many cancer derived cell lines and tumor samples show elevated expression of Tdp1 (, unpublished observations)." (PMID 31698852, 2019). "In this study, TDP1 knockdown enhanced the sensitivity of cancer cells to carboplatin and resulted in more significant DNA damage." (PMID 31235732, 2019). "Many Tdp1 substrates are generated by chemotherapeutics linking Tdp1 to cancer drug resistance, making a compelling argument to develop small molecules that target Tdp1 as potential novel therapeutic agents." (PMID 31875206, 2019). "Because TDP1 also has 3′-nucleosidase activity, several studies have shown that TDP1 is also important in repairing DNA damage induced by anti-viral and anti-cancer nucleoside analogs." (PMID 31226795, 2019). "To date, many catalytic Tdp1 inhibitors have been identified, yet only a few were tested in cell or cancer models." (PMID 31875206, 2019).
cancer (continued). "Because Tdp1 repairs Top1/DNA cleavage complexes induced by CPTs, inhibitors of Tdp1 can enhance the sensitivity of cancer cells to CPT analogues." (PMID 31878088, 2019). "Cancer cells often lack these alternative pathways, thus relying only on the Tdp1-mediated repair to face TopI poisons." (PMID 29597329, 2018). "The hTdp1 (human tyrosyl-DNA phosphodiesterase 1) inhibitor NSC120686 has been used, along with topoisomerase inhibitors, as a pharmacophoric model to restrain the Tdp1 activity as part of a synergistic treatment for cancer." (PMID 29597329, 2018). "In summary, this study identifies UCHL3 as a regulator of chromosomal SSB repair by controlling TDP1 proteostasis and highlights it physiological significance in neurological disease and cancer." (PMID 29898404, 2018). "TDP1 plays an essential role in the resistance of cancer cells to currently used antitumour drugs based on Top1 inhibitors such as topotecan and irinotecan." (PMID 30191738, 2018). "In cancer cells, however, TDP1 counters the action of camptothecin by repairing drug-created stalled topo I-DNA complexes, thus making TDP1 a potential anticancer target." (PMID 29258235, 2017). "TDP1 expression had a significant correlation with NRF-1 expression in the NCI-60 human-tumor cell-line panel as well as in the Cancer Cell Line Encyclopedia." (PMID 28993637, 2017). "Our reported yeast observations suggested that TDP1 is a suitable target to turn a DNA repair enzyme into a cellular toxin as a potential novel anti-cancer treatment strategy." (PMID 27893431, 2016). "What's more, most TDP1 substrates are formed by clinically active (chemo-)therapeutics and endogenous reactive oxygen species whose levels are elevated in cancer cells." (PMID 27893431, 2016). "In summary, these results support the potential of targeting TDP1-cc as a novel anti-cancer treatment strategy, which will act synergistically with chemotherapeutics that induce DNA adducts that function as TDP1 substrates." (PMID 27893431, 2016). "415, 741-758, 2012), we propose that converting TDP1 into a cellular poison by stabilizing the covalent enzyme-DNA intermediate is a novel therapeutic strategy for cancer treatment." (PMID 27893431, 2016). "TDP1 is subject to posttranslational modifications that control its cellular activity such as phosphorylation and SUMOylation; however the contribution of these modifications to TDP1 cellular function in cancer remains elusive." (PMID 24637157, 2014). "In summary, these data demonstrate a role for TDP1 in response to alkylation damage in human cells and illustrates the potential application of this knowledge to improve alkylation-based cancer therapy." (PMID 24335147, 2014). "Here we focused on determining the tyrosyl DNA phosphodiesterase activity of TDP1, which is the preferred activity in vivo and in vitro, and is likely to be exploited in conjunction with camptothecin-derived protocols for cancer therapy." (PMID 24637157, 2014). "Inhibition of TDP1 is therefore an attractive strategy for targeting cancer cells in conjunction with TOP1 poisons." (PMID 24637157, 2014). "In this study, we identified TDP2 as a susceptible gene in the absence of TDP1 to target cancers with radiomimetic drugs." (PMID 40155951, 2025). "It follows that Tdp1-targeting chemical inhibitors could synergize well with existing chemotherapy drugs to deny cancer growth; therefore, identification of Tdp1 inhibitors may advance precision medicine in oncology." (PMID 39338235, 2024). "The discovery of Tdp1 inhibitors could unlock more treatment regimens for cancer patients, allowing for therapies tailored to the patient’s condition." (PMID 39338235, 2024).
cancer (continued). "Thus, the application of TDP1 inhibitors in cancer treatment would increase the toxicity of anticancer therapeutics targeted at topoisomerases." (PMID 39596476, 2024). "Thus, TDP1 plays an important role in maintaining genome stability and is considered as a potential therapeutic target in cancer treatment." (PMID 36982223, 2023). "Thus, a new structural series of TDP1 inhibitors, which are able to sensitize cancer cells to the topotecan cytotoxic effect has been discovered." (PMID 37298106, 2023). "Thus, we developed a new structural type of potent TDP1 inhibitors which are promising for further pharmacological studies as adjuvant therapy against cancer in combination with Top 1 poisons, such as topotecan." (PMID 37298106, 2023). "Thus, targeting TDP1 is expected to result in minimal toxicity but has the potential to selectively sensitize cancer cells over normal cells to TOP1 poisons." (PMID 35869071, 2022). "In addition, we showed that co-inhibition of TDP1 and DSB repair pathways enhanced cellular sensitivity to CPT treatment, which provides guidance for the further development of TDP1 inhibitors for cancer therapy." (PMID 35869071, 2022). "Other authors also noticed that TDP1 together with PARP1 inhibition could be a successful cancer treatment strategy." (PMID 34768766, 2021). "In cancer HeLa cells, all four TDP1 inhibitors showed promising synergy in conjunction with Tpc." (PMID 34356597, 2021). "It has been reported the altered expression of TDP-1 in several cancers." (PMID 33536086, 2021). "Additionally, TDP1 has been suggested as a promising target in the treatment of HPV-induced cancers, where it, along with PARP1, has been shown to be essential for the initial amplification of the high-risk HPV genome." (PMID 34300575, 2021). "TDP-1 constitutes a promising target in cancer treatment; therefore, the development of inhibitors may be useful to improve the efficacy of chemotherapy." (PMID 33536086, 2021). "Thus, TDP1 is a promising therapeutic target for the development of drug combinations with topotecan, as well as other drugs for cancer treatment." (PMID 34356597, 2021). "Thus, a promising approach to increase the selectivity and potency of TOP1 poisons to cancer cells is to combine them with TDP1 inhibitors, which can significantly increase the chemotherapeutic efficacy." (PMID 32751997, 2020). "Our results allow speculating TDP1 inhibition as a factor to increase OGG1-mediated DNA damage in cancer cells which lost redox homeostasis resulting in oxidative DNA damage." (PMID 33505969, 2020). "Tyrosyl-DNA phosphodiesterase 1 (Tdp1) is a promising therapeutic target in cancer therapy." (PMID 31619021, 2019). "Furthermore, increased Tdp1 expression counteracts the cytotoxicity of CPTs, and is frequently observed in cancers resistant to CPT therapy." (PMID 31878088, 2019). "Nevertheless, only a few Tdp1 inhibitors have been tested in cell- or cancer-models." (PMID 31878088, 2019). "In addition, TDP1 possesses the versatility of precisely hydrolyzing a variety of 3’ adducts from DNA, and therefore, the screening of TDP1 inhibitors is a promising avenue for developing new cancer therapies." (PMID 31547492, 2019). "However, cancer cells can resist TOP1 targeting therapies by overexpression of PDB repair factors such as TDP1." (PMID 29898404, 2018). "The combination of drugs acting on Top1 and TDP1 can significantly increase the effectiveness of chemotherapy and allow to reduce total toxicity on the organism through reducing the therapeutic dose of these anti-cancer drugs." (PMID 30191738, 2018). "Indeed, the herein described observations support that molecular targeting to stabilize the TDP1-DNA intermediate is a potential novel cancer treatment strategy." (PMID 27893431, 2016). "Overall, these results support the hypothesis that stabilization of the TDP1-DNA covalent intermediate is a potential anti-cancer therapeutic strategy." (PMID 27893431, 2016).
cancer (continued). "Thus, uncompetitive TDP1 inhibitors could lead to the accumulation of the single-strand breaks in cancer cells." (PMID 34768766, 2021). "Consequently, targeting TDP1 might be a promising strategy to sensitize cancer cells to platinum in clinic." (PMID 31235732, 2019). "Thus, in contrast to inhibiting TDP1 activity, stabilization of the TDP1-DNA reaction intermediate might be a more efficacious therapeutic approach to treat cancer." (PMID 27893431, 2016). "Finally, to examine whether the involvement of TDP1 in MMS damage could be applied to improve alkylation-based chemotherapy, we screened a panel of cancer cell lines for TDP1 expression." (PMID 24335147, 2014). "The discovery of this novel TDP2-dependent repair of DSBs resulting from radiomimetic drug exposure indicates that TDP1 and TDP2 inhibition in combination with radiomimetic drugs represents a strategy for cancer treatment." (PMID 40155951, 2025). "Elucidation of the TDP2-dependent repair pathway for DSBs induced by radiomimetic drugs revealed that the combination of radiomimetic drugs, TDP1 inhibitors, and TDP2 inhibitors can be used for cancer treatment." (PMID 40155951, 2025). "A mechanism employed by cancer cells to resist killing by TOP1 poisons is the overexpression of enzymes capable to repair TOP1-DNA breaks, such as tyrosyl-DNA-phosphodiesterase 1 (TDP1)." (PMID 39109293, 2024). "Our data indicate that MUS81 and TDP1 play independent roles in the repair of CPT-induced lesions, thus representing new therapeutic targets for cancer cell sensitisation in combination with TOP1 inhibitors." (PMID 37194054, 2023). "Several authors discuss the rationale behind the use of the combination of TOP1 poison and TDP1 and PARP inhibitors in cancer treatment." (PMID 36982223, 2023). "On the other side, the NSC120686 compound was recently identified based on virtual screening of pharmacophores able to inhibit human Tdp1 and subsequently used in combination with CPT-derivates to inhibit the growth of different cancer cell lines." (PMID 33767724, 2021). "The concentrations of the Tdp1 inhibitors are 5 μM for HeLa cells and ranged from 15 to 45 μM (concentration is given in parenthesis in μM) for the HCT-116 cancer cell line." (PMID 34073771, 2021). "Since TDP1 and TDP2 are rational anti-cancer drug targets, it will be beneficial to verify how potential inhibitors will impact TDP1 and TDP2 in the nucleus vs the mitochondria." (PMID 31226795, 2019). "Inhibitors of Tdp1, together with its activator, PARP1, and topoisomerase I inhibitors are considered viable drugs in cancer therapy." (PMID 28182794, 2017). "TDP1 is a critical enzyme for TOP1-DPCR and is a promising target for cancer treatment." (PMID 37788708, 2023). "In this work, it was shown that the combined use of topotecan and Tdp1 inhibitor, the hydrazonothiazole derivative of usnic acid OL9-119, leads to an increase in the DNA-damaging effect of topotecan which is used in the clinic for the treatment of cancer." (PMID 36653585, 2023). "However, the nucleolytic pathway may not be as effective in cancer cells which often have mutated or inactivated DNA checkpoints required for endonuclease activation, potentially making them more dependent on repair mediated by proteases and TDP1." (PMID 37788708, 2023). "The authors also noticed that TDP1 and PARP1 inhibitors might also be effective against HPV-induced cancer." (PMID 34768766, 2021). "A decrease in TDP1 activity in the U87 cell, by either knockdown or inhibitor, would be expected to decrease the IC50 of this relatively resistant GBM cell line for other cancer cell lines." (PMID 31547492, 2019). "At least five of the inhibitors block the function of Tdp1 and PARP1, which have been identified as essential cellular proteins for HPV replication and promising candidates for the development of antivirals against HPV and possibly against HPV-related cancers." (PMID 28182794, 2017).
cancer (continued). "Benzylidene derivatives of usnic acid, a discovered Tdp1 inhibitor, have shown to exhibit a half-maximal inhibitory constant (IC50) value of 100 μM against neoplastic cells and managed to reduce tumor sizes by 62–65%, confirming the cancer-impeding effects of Tdp inhibitors." (PMID 39338235, 2024). "Therefore, the combination of TDP1 inhibitors and TOP1 poisons could synergistically be more effective for the treatment of cancer." (PMID 39109293, 2024). "Importantly, the most active TDP1 inhibitor demonstrated a significant synergistic effect with anticancer drug topotecan against the HeLa cancer cell line but not against HEK293A cells." (PMID 37298106, 2023). "Recent data have shown that high levels/activity of TDP1 can negatively impact the success of therapy with TOPO1 inhibitors as there is a higher degree of TOPO1-damage reversal thus negating the ensuing DNA damages and cell death signal imparted in the cancer cell." (PMID 36120345, 2022). "Given that Tdp1 inhibitors are supposed to be used in therapeutic cocktails, it is important that they do not exert their own toxicity and do not enhance the existing adverse effects of cancer therapy." (PMID 32823658, 2020). "ZW-1266 is a cell-permeable deazaflavin analog that selectively inhibits TDP2, but not TDP1 enzymatic activity in vitro, and strongly sensitizes cancer cells toward the treatment of ETP, a phenotype consistent with the TDP2 function loss and leads to the Top2cc formation." (PMID 32193368, 2020). "Moreover, the potential development of Tdp1-poisons, compounds that selectively increase the lifetime of Tdp1-DNA adducts similar to Tdp1 catalytic mutants such as the SCAN1 mutant, would be a welcome addition for combinational treatment options for anti-cancer therapy." (PMID 31875206, 2019). "Although Tdp1 is a non-essential enzyme, it plays an important role in maintaining cellular homeostasis, while dysregulation of Tdp1 enzyme levels or catalysis can drive human pathology such as neurodegeneration and cancer." (PMID 31698852, 2019). "Moreover, as Tdp1 and PARP1 are necessary for cancer cell survival, their inhibitors may also be effective against HPV-induced cancer." (PMID 28182794, 2017). "TDP1 inhibitors are currently being explored in clinical trials to sensitize cells to topoisomerase inhibitors and could be also used in conjunction with HMCES depletion/inhibition to sensitize cancer cells to APOBEC3 expression and perhaps other agents that generate AP sites." (PMID 33788831, 2021). "Next, we checked the cytotoxic effect of the combination of Tpc and 11a–d as compared to Tpc in the HeLa cancer cells and non-cancerous HEK293A WT and TDP1-/- cells." (PMID 34356597, 2021).